CD4 (CD4 molecule)
Diseases named in the same sentence as CD4 in open-access papers (continued):
Sharing a sentence is not in itself a finding about the gene and the disease.
Hepatitis (continued). "CD4+ T cell count <200 cells/μL was an independent risk factor for elevated liver fibrosis scores regardless of hepatitis status." (PMID 26979535, 2016). "CD25+Foxp3+ CD4 T cells accumulated in the liver in the course of CD8 T cell-mediated hepatitis." (PMID 26599014, 2015). "Moreover, CD4+ cell depleted mice showed overt hepatitis, as indicated by significantly elevated serum ALT levels." (PMID 24466045, 2014). "Since provision of help to CD8 T-cells is one of the main tasks of CD4 T-cells, we examined whether hepatitis induced by CD8 T-cells is augmented by addition of CD4 T-cells." (PMID 21779338, 2011). "Further, most hepatitis A cases reported was from poor hygienic surroundings, which emphasizes the need for improving the public health measures to prevent epidemics of hepatitis A. There was relative percentage of CD4+ T lymphocytes decline and CD8+ T lymphocytes increase in the fulminant HAV." (PMID 21605420, 2011). "For example, lower VLs have been associated with improved responses to hepatitis A, hepatitis B and varicella vaccinations independent of CD4 count." (PMID 22194853, 2011). "One study addressing the development of irAE hepatitis in patients receiving ICB for melanoma found an association between HCMV reactivation over winter, putatively triggered by metastatic disease or intercurrent unrelated infections, and the expansion of CD4⁣+ TEM cells." (PMID 41194666, 2025). "Another study showed that increased numbers of circulating IL-10+ Bregs and CD4+CXCR5+Foxp3+ follicular regulatory T (TFR) cells are associated with poor virus eradication and liver injury in CHB patients and that serum IL-10 levels are associated with hepatitis flare." (PMID 35163476, 2022). "Our inability to detect CMV in baseline serum samples from CD4+ TEMhigh patients or liver biopsies from patients with high-grade hepatitis is a challenge for our theory; however, it may simply be beyond our technical capability to detect very low levels of compartmentalised viral reactivation." (PMID 33664251, 2021). "Though it remains to be determined whether DH also suppressed CD4+ T-cell proliferation in ConA-induced hepatitis model, the disparity regarding the mechanism of DH in suppressing cytokine production by CD4+ T cells reveals that DH may play distinct roles under different disease conditions." (PMID 33117376, 2020). "We excluded inhibitory effects of CPZ on T-cell activation in vivo and another study also showed that CPZ did not affect inflammatory cytokine production during Con A-induced hepatitis which could be possible reasons for the reduced hepatic infiltration of effector CD4+ T cells." (PMID 26052942, 2015). "However, our experiments suggest that CD4+ T cells also play a role in the induction of hepatitis." (PMID 21966366, 2011). "Of 32 HIV-positive patients, 1 (3.1%) had a CD4 count > 500 per mm3, undetectable viral load, and was taking ART intermittently because of hepatitis-induced liver cirrhosis with a history of transhepatic intrajugular portosystemic shunting." (PMID 39450395, 2024). "The infiltration of liver tissue was found to be dominated by CD4+ and CD8+ T cells, and T‐cell depletion abolished ICI‐mediated hepatitis." (PMID 39001676, 2024). "Helper CD4+ T cells play a critical role in the pathogenesis of Con A-induced hepatitis, so we further identified the proportion of liver-infiltrating Th1 (CD4+IFN-γ+) and Th17 (CD4+IL-17A+) subsets." (PMID 37775797, 2023). "In Con A-induced hepatitis mice, CD73 expressing ERCs reduced CD4+ T cell infiltration in livers, and inhibited Th1 and Th17 cell differentiation in splenocytes while promoting the generation of Tregs." (PMID 37775797, 2023). "In this review, we focus on T cells and in particular CD4+ T cells and discuss the role of different subsets of CD4+ T cells including Th1, Th2, Th17, Th22, and Treg in NASH-related liver inflammation and fibrosis." (PMID 36032141, 2022).
Hepatitis (continued). "The ratios of inflammatory cells CD4/CD8, and CD138/CD3 in ICIs-related hepatitis were significantly lower than those in AIH or DILI patients (p < 0.05)." (PMID 35256688, 2022). "The proportions of CD4+, CD8+, activated CD8+, activated CD4+ T cells and the ratio of Th1/Th2 were obviously elevated in hepatitis." (PMID 36457713, 2022). "In contrast, DAX1 ablation in hepatocytes stimulates the attraction of CD4+ and CD8+ T cells to the liver, accelerating the development of ConA-induced hepatitis." (PMID 36430486, 2022). "The spatial proximity between CD6+CD4+ T cells and ALCAM+ hepatocytes is observed in the interface hepatitis lesion." (PMID 36159854, 2022). "We first defined the effects of AAV-mIL-30 in vivo by administering it to a well-known concanavalin A (ConA)-induced hepatitis model of mice and found that AAV-mIL-30 reduced the numbers of activated CD25+CD4+ T cells and the levels of serum IFN-γ and IL-12." (PMID 34440235, 2021). "The results have demonstrated that Gal-9 high-expressing ERCs restored liver function, ameliorated liver pathological damage, decreased the number of CD4+ and CD8+ cell, and inhibited Th1 and Th17 cell proliferation in the hepatitis mice." (PMID 34654474, 2021). "For instance, purple is only for CD4 count, FBC and HIV viral load, green is for biochemistry and red is for RPR and hepatitis." (PMID 31412849, 2019). "It is quite important to notice that the liver macrophages are responsible for the proliferation of CD4+ T cells and generation of IFN-γ-producing Th1 cells in Con A-induced hepatitis." (PMID 27679638, 2016). "We quantified the fraction of hepatic CD4+ T cells expressing CXCR3, the receptor for CXCL9 and CXCL10 that were strongly up-regulated at an early stage of Con A-induced hepatitis." (PMID 26052942, 2015). "For example, in a mouse model of hepatitis, the galectin-3 inhibitor attenuated liver damage and proinflammatory T cell-mediated cytokine release (IFN-γ- and IL-17- and IL-4 producing CD4+ T cells)." (PMID 25387690, 2014). "Adaptive immune responses, especially of the CD4+ and CD8+ T cells and the Treg, have strong effects in post-OLT hepatitis C viral recurrence and in recurrent hepatitis activities." (PMID 25215259, 2014). "As in concanavalin A hepatitis, CD4+ T-cells regulate immune responses in anesthetic DILI; however, in anesthetic and other drug-induced DILI, hepatitis is predominantly neutrophilic." (PMID 23577207, 2013). "As a prelude to exploring the value of manipulating TIM-3/galectin-9 interaction to influence the outcome of Con A-induced hepatitis, mice were injected with Con A and the expression pattern of TIM-3 on CD4+ T cells was measured at various times in the spleen." (PMID 23118999, 2012). "Acute HEV hepatitis can occur in HIV-infected patients but rarely explains cryptogenic hepatitis, at least in an urban HIV population, regardless geographic origin and CD4 counts." (PMID 21496215, 2011). "Using expansion of CD4⁣+ TEM populations, in combination with HCMV status, the authors predicted hepatitis risk, although this was not linked to HCMV seropositivity alone." (PMID 41194666, 2025). "In univariate analyses, dataset restriction identified new biomarkers associated with ICI-related hepatitis, including CD27+ CD28+ CD4+ TEM cells, that were not returned by conventional methods." (PMID 38926389, 2024). "CD4+ T cell is important for Con A-induced hepatitis, the proportions of pro-inflammatory CD4+ T cell subsets in splenocytes were further analyzed by flow cytometry, including Th1 (CD4+IFN-γ+) and Th17 (CD4+IL-17A+) cells." (PMID 37775797, 2023). "Even though European EACS guidelines recommend that persons lacking anti-HAV IgG antibodies should be offered vaccination to prevent HAV infection regardless of their CD4+ T-cell count, vaccination against hepatitis A in the region is insufficient." (PMID 37243084, 2023).
Hepatitis (continued). "From the health to hepatitis, the MIF signaling network and related ligand-receptor interactions, including MIF-(CD74 + CXCR4), MIF-(CD74 + CXCR2), and MIF-(CD74 + CD44) showed a significant effect on macrophage–naïve CD4 + T cell interaction." (PMID 36221095, 2022). "Our study used a related approach to profile immune responses in a cohort with comparable baseline patient characteristics but did not identify the reported relationship of hepatitis incidence connected to CD4 TEM cells." (PMID 36503532, 2022). "From hepatitis to cirrhosis, the total interactions of the CCL signaling pathway increased significantly, and both the strength of autocrine and paracrine cells from macrophages and naïve CD4 + T cells, increased in the CCL signaling pathway." (PMID 36221095, 2022). "From hepatitis to cirrhosis, the CCL signaling network and related ligand-receptor interactions, including CCL5-CCR5 and CCL5-CCR1, presented the highest communication probability in macrophage-naïve CD4 + T cell interaction." (PMID 36221095, 2022). "Furthermore, treatment with Gal-9 high-expressing ERCs restored liver function, ameliorated liver pathological damage, inhibit CD4+ and CD8+ T cell proliferation and suppress Th1 and Th17 cell response in the hepatitis mice." (PMID 34654474, 2021). "Thus, IL-35 not only eliminated the function of CD8+ T cells in a direct way, but also reduced IL-9 production by CD4+ T cells, and in turn, would lead to a suppression in CD8+ T cell-mediated cytotoxicity in hepatitis and HCC patients." (PMID 34177894, 2021). "The low response to hepatitis B vaccine presented lower frequencies of cTfh cells, but not CXCR5−CD4+ T cells, than HR, indicating that cTfh cells rather than other CD4+T cell subsets were a better marker for poor responses to hepatitis B vaccination." (PMID 33794763, 2021). "The 50th, 75th and 90th percentiles of time-to-hepatitis in CMV-IgG+ patients were 24, 52 and 84 days, respectively; therefore, we treated four CMV IgG+ CD4+ TEM≥16% patients receiving αPD-1/αCTLA-4 therapy with prophylactic valganciclovir for between 4 and 23 weeks." (PMID 33664251, 2021). "Baseline expansion of CD4+ TEM cells was a fair discriminator (AUROC = 0.706) of patients who did or did not later develop hepatitis in the validation set." (PMID 33664251, 2021). "We have found that DPPS pretreatment significantly enhances percentages of FoxP3+ regulatory CD4+ and CD8+ cells in the livers of mice with ConA-induced hepatitis and enhances the percentage of activated CD69+CD25+ T cells, but decreases percentage of inflammatory IL-17+ and IFN-γ+ T cells." (PMID 33809904, 2021). "Consistently, in hepatitis with alcoholic liver disease, CXCR4 dependent migration of lymphocytes into the tissue is significantly increased in response to treatment with ethanol, resulting in recruitment of CD4+ and CD8+ lymphocytes into liver tissue." (PMID 34386499, 2021). "Further, the data from FCM detection suggested expression of IL36 was higher in CD4+ T cells than in CD8+ T cells, and was the highest in HCC patients compared with hepatitis patients and healthy controls, this highlighted that IL36 was probably mainly from the CD4+ T cells of PBMC." (PMID 33033508, 2020). "Through upregulated Tregs, IL-33 exerts a negative effect on CD4+ T cell proliferation and alleviates hepatitis." (PMID 31787967, 2019). "Furthermore, Notch signaling pathway promoted IL-22 production by both CD4+ T cells and ILC22 in Concanavalin A-induced hepatitis and chronic viral hepatitis." (PMID 30473538, 2018). "In contrast, numbers of CD4+ or CD4+CD25+Foxp3+ T cells in the spleen did not significantly change during the course of hepatitis." (PMID 26599014, 2015). "We investigated whether the number of CD4 T cells present in liver and spleen changes during CD8 T cell-mediated hepatitis." (PMID 26599014, 2015).
Hepatitis (continued). "In the present study, using an established model of ConA-induced hepatitis, we demonstrate that the MDSCs are involved in T cell-mediated liver injury and that MDSC-mediated suppression of early CD4+CD69+ T cells proliferation can protect mice from ConA-induced hepatitis through ROS pathway." (PMID 24981055, 2014). "In the model of Con A-induced hepatitis, since inflammation appeared to be mainly orchestrated by IFN-γ producing CD4+ T cells, we investigated the effects of galectin-9 on the induction of apoptosis of CD4+ T cells." (PMID 23118999, 2012). "No significant increase in ALT-levels was observed after transfer of 4 million naïve or effector OT-II T-cells into TF-OVA mice, demonstrating that neither naïve nor effector CD4 T-cells are sufficient to induce hepatitis." (PMID 21779338, 2011). "Gender, body weight, baseline CD4 cell counts, or receiving fluconazole were not predictive of clinical hepatitis." (PMID 16120209, 2005). "Thus, age and CMV infection may both contribute to expansion of TEM CD4 responses and affect the incidence ICB-hepatitis." (PMID 36503532, 2022). "Multiple hypo-methylated genes have been described in the CD4+ and CD19+ T lymphocytes of patients with autoimmune hepatitis, and the circulating micro-ribonucleic acids, miR-21 and miR-122, have correlated with laboratory and histological features of liver inflammation." (PMID 35844554, 2022). "Furthermore, we observed that macrophage-naïve CD4 + T cell interaction had an important effect on the cirrhosis and cancer but not the hepatitis." (PMID 36221095, 2022). "We speculate 4 of 23 CMV IgG+ CD4+ TEM<16% patients who were incorrectly predicted as hepatitis-negative (pink box) were sampled at an early stage of CD4+ TEM cell expansion and our test was not sensitive enough to discriminate the change." (PMID 33664251, 2021). "Expression of MHC class II molecules is typically restricted to professional antigen-presenting cell types such as Kupffer cells, and not hepatocytes; however, hepatocytes from humans with clinical hepatitis do express MHC class II molecules, which may be capable of attracting CD4+ T lymphocytes." (PMID 34573524, 2021). "Three of four CD4+ TEM≥21% patients assigned to αPD-1 monotherapy instead of αPD-1/αCTLA-4-treatment did not develop hepatitis as predicted; therefore, baseline CD4+ TEM expansion could be taken as a relative contraindication to dual therapy." (PMID 33664251, 2021). "Following amelioration of hepatitis, the (CD4/CD8) ratio became normalized (data not shown)." (PMID 32908853, 2020). "Despite the highly effectiveness of the standard hepatitis B vaccination regimen at 6 months after completion, the long-term immunogenicity was lower than the four double doses regimen among HIV-infected adults with CD4+ cell counts > 200 cells/mm3 and undetectable plasma HIV-1 RNA." (PMID 31711528, 2019). "Mice lacking CD4+ T cells were fully protected against Con A-induced hepatitis." (PMID 29643811, 2018). "We showed that the strongly increased recruitment of transferred CD4+ T cells into the inflamed liver of Con A-treated mice was abolished after administration of CPZ during hepatitis whereas the clathrin inhibitor did not influence CD4+ T-cell migration to the healthy liver." (PMID 26052942, 2015). "The combination of naive OT-II and OT-I T-cells did not increase the severity of hepatitis compared to OT-I T-cells alone, even when transfer of CD4 T-cells preceded the transfer of CD8 T-cells by three days to ensure presence of CD4 T-cells in the liver at the time of CD8 T-cell priming." (PMID 21779338, 2011). "CD4 T-cells were not required for the induction of hepatitis by CD8 T-cells." (PMID 21779338, 2011). "Moreover, TUNEL-FITC and CD4-PE co-staining analysis showed that TUNEL positive cells were mostly colocalized with liver CD4+ T cells in asiatic acid-treated mice, suggesting that asiatic acid induces apoptosis of intrahepatic CD4+ T cells in Con A-induced hepatitis in mice." (PMID 23029367, 2012).
Hepatitis (continued). "During AIH development, a lack of self-tolerance increases the number autoreactive CD4+ and CD8+ T cells, driving excess inflammation and culminating in the sustainment of hepatitis." (PMID 35720411, 2022). "Others have shown that CD4+ T cells from HIV infected individuals failed to secrete IFN-γ by ex vivo ELISpot after stimulation with Hepatitis B, Hepatitis A and tetanus toxoid." (PMID 23840618, 2013). "Blood work showed microcytic hypochromic anemia (Hb = 11,2 g/dL), ferritin 5,5 ng/mL, LDH 300U/L, liver and kidney functions tests were normal; hepatitis B and C testing were negative; HIV RNA viral load 84 copies/mL, CD4-T 119 cells/mL, CD8-T 1175 cells/mL, CD4/CD8 = 0,1." (PMID 36827036, 2023). "Hence, we observed no hepatitis in the four valganciclovir-treated patients, whereas 15 of 17 (88.2%) CMV IgG+ CD4+ TEM≥16% patients treated with αPD-1/αCTLA-4 and no valganciclovir prophylaxis developed clinical hepatitis." (PMID 33664251, 2021). "Strikingly, despite liver inflammation, migration of CD4+ T cells into the liver was significantly reduced if mice received CPZ in addition to Con A. CPZ itself did not influence hepatic migration of transferred CD4+ T cells in healthy mice." (PMID 26052942, 2015). "Moreover, some clinical covariates that influence the intensities of immune deterioration and immune recovery, may not have been included, for example, CD4/CD8 ratio and hepatitis status." (PMID 32228523, 2020).